BDNF (brain derived neurotrophic factor)
Diseases named in the same sentence as BDNF in open-access papers (continued):
Sharing a sentence is not in itself a finding about the gene and the disease.
memory impairment (continued). "Taken together, these results indicate that a mixture of SC and RF extracts prevents scopolamine-induced long-term spatial learning and memory impairment, through activation of BDNF-induced signaling cascade." (PMID 31547274, 2019). "In our study, we evaluated memory impairment using behavioral tests, and quantified endocannabinoids and BDNF expression after the administration of JWH-018 in mice." (PMID 31270353, 2019). "Oral administration of DW2009 in the AD mouse model attenuated memory impairment and inhibited amyloid-β expression, a major pathologic finding of AD, by regulating gut microbiota composition and increasing BDNF expression." (PMID 30717153, 2019). "Selective PDE2 inhibitor Bay 60-7550 was able to enhance Aβ1–42-induced cognitive and memory impairment through regulating the HPA axis, causing rises in BDNF levels and pCREB." (PMID 31632240, 2019). "The memory impairment showed a significant positive correlation with low brain-derived neurotrophic factor (BDNF) expression in the hippocampus of these rodents." (PMID 29200666, 2017). "The neurons of the hippocampus of aged animals showed a down-regulation of BDNF and p-CREB expression, associated with learning and memory impairment, which was also similar with our result." (PMID 28430606, 2017). "The link between decreased BDNF concentrations and the severity of amnestic syndrome indicates a key role of BDNF in memory impairment among MNCD-AD patients." (PMID 27597800, 2016). "Steamed and fermented C. lanceolata ameliorated amyloid-β–induced memory impairment and this effect appears to be mediated via the inhibition of AChE activity and the activation of BDNF, p-CREB, and ERK signaling." (PMID 27313637, 2016). "Decreased plasma BDNF highly correlated with the severity of memory impairment and total MMSE score in MNCD-AD group." (PMID 27597800, 2016). "In the present study, we have shown that 7,8‐DHF can improve propofol‐induced learning and memory impairments and can up‐regulate the decreased levels of BDNF and TrkB transcripts and proteins in the hippocampus of rat offspring that are exposed to propofol." (PMID 27297627, 2016). "Physical exercise reversed high-fat diet-induced hippocampal-dependent memory impairment and increased BDNF expression in CA3 of the hippocampus." (PMID 26368803, 2015). "Acupuncture stimulation also produced increased cholinergic enzyme activity, BDNF and CREB immunoreactivity, and increased CHT1, VAChT, BDNF and CREB mRNA expression in the hippocampus associated with SCO-induced memory impairment in male rats." (PMID 25231482, 2014). "It is known that both NGF and BDNF have been found to enhance acetylcholine release, while deficiencies in acetylcholine release and BDNF or NGF expressions are related to memory impairment in AD patients, as mentioned in the introduction." (PMID 23651534, 2013). "We first determined brain BDNF protein levels using an ELISA assay in female APdE9 mice at the age of 12 months, when memory impairment begins to manifest in these mice." (PMID 23844236, 2013). "Neural stem cells have been shown to rescue memory impairment in AD model mice by releasing brain-derived neurotrophic factor (BDNF)." (PMID 23049854, 2012). "Additionally, reductions in hippocampal brain-derived neurotrophic factor (BDNF) levels were reported to correlate with spatial memory impairments." (PMID 40290018, 2025). "Interestingly, BDNF levels correlate with LTP and associated learning and memory impairments in juvenile male mice subjected to CA/CPR, with levels decreasing at 7 days and recovering to sham levels at 30 days." (PMID 40386541, 2025). "Additionally, abdominal exploratory surgery in anesthetized mice induced H3K9 trimethylation, which enhanced binding to the BDNF exon IV promoter, leading to reduced BDNF expression and memory impairment." (PMID 40914484, 2025).
memory impairment (continued). "For example, a study published in Fish Physiology and Biochemistry showed that betanin treatment protected zebrafish against SCO (100 μM)-induced memory impairments and oxidative stress by normalizing AChE activity, enhancing BDNF expression, and reducing MDA levels." (PMID 41155598, 2025). "Our findings are in agreement with previous studies showing the beneficial effect of genistein treatment, which ameliorated memory impairment in the mice by significantly increasing BDNF expression level and CREB phosphorylation in lipopolysaccharide (LPS)-treated mice." (PMID 41354896, 2025). "Decreased BDNF level is involved in neurodegeneration and memory impairment." (PMID 38333757, 2024). "Also, the combination of stem cells and NPs has been found to increase BDNF expression and improve neurological deficits in brain injuries and memory impairment in a transgenic mice model of AD." (PMID 39229584, 2024). "SCOP‐induced memory impairment can be attenuated by regulating the ERK/CREB/BDNF signaling pathway." (PMID 39056330, 2024). "Collectively, these findings suggest that (S)-ketamine may improve spatial working memory impairment in CCI mice through the butyric acid – BDNF – TrkB pathway." (PMID 38332676, 2024). "Hence, given the pivotal role of BDNF in synaptic plasticity and neural circuit regulation, elevated BDNF expression abrogated HFD‐induced memory impairment." (PMID 36776763, 2023). "Encouragingly, Angelica sinensis polysaccharides exhibited promise in reducing acetylcholinesterase (AChE) levels, elevating acetylcholine (ACh) and choline acetyltransferase (ChAT) levels, and improving memory impairment in AD rats through the BDNF/CREB pathway." (PMID 38075226, 2023). "However, both elevated and reduced levels of BDNF can disrupt inhibitory and excitatory neurotransmission in the brain, leading to a decline in synaptic refinement and memory impairment." (PMID 38075212, 2023). "BDNF and TrkB protect against memory impairment and modulate neurogenesis in the hippocampus." (PMID 37242234, 2023). "So, we propose the hypothesis that inhibition of ATAXIN by ASO7 may consistently increase BDNF expression, thereby ameliorating memory impairments in sleep‐deprived mice." (PMID 37072935, 2023). "Similarly, we demonstrated a positive correlation between BDNF levels in the hippocampus and mPFC as well as memory impairment in the Ket-induced model, as assessed by the IA test." (PMID 37649038, 2023). "Treadmill exercise ameliorated memory impairment and increased hippocampal dendritic length, neurogenesis, and BDNF expressions in the amyloid-beta injected rats, suggesting that exercise may have therapeutic benefits for relieving symptoms of AD." (PMID 37970437, 2023). "Thus, the present study supports a potential link between particular intestinal bacterial taxa, M2 microglia, the BDNF signaling system, and spatial learning and memory impairment after chronic METH exposure." (PMID 37212669, 2023). "In this study, we proposed and tested the hypothesis that ASOs targeting ATXN2 in the basal forebrain could increase BDNF expression, thereby modulating sleep deprivation‐induced memory impairments." (PMID 37072935, 2023). "We selected the basal forebrain as the brain area for drug injection in this study to observe whether basal forebrain BDNF signaling activation by ASO targeting ATXN2 mRNA could reverse the memory impairments induced by sleep deprivation." (PMID 37072935, 2023). "Moreover, CGA mitigated memory impairment and reversed the inhibition of the neurotrophic factors brain-derived neurotrophic factor (BDNF) and nerve growth factor (NGF), alleviating nerve injury." (PMID 36771496, 2023). "Taken together; BRB may be a valuable preclinical treatment for improving memory impairment through BDNF expression in PFC and hippocampus, therefore; BRB is suggested for memory disturbances induced by T. gondii infection." (PMID 37649038, 2023).
memory impairment (continued). "Interestingly, reduced BDNF gene expression in hippocampal tissues of AppNL−G−F mice overlaps with the same age (6 months) when the first sign of memory impairment appears." (PMID 37596686, 2023). "Together, these data suggest that the BDNF/TrKB/CREB signaling pathway may account for the improved effects of APN treatment on KA-induced memory impairment." (PMID 37456525, 2023). "In humans, loss of function of BDNF and its receptor TrkB, as well as SH2B1 deficiency, have been associated with speech and language delay, behavioral abnormalities, and memory impairment, features overlapping the behavioral and cognitive phenotypes seen in deletion carriers." (PMID 37586323, 2023). "In addition, polydatin ameliorated memory impairment in animal models via upregulation of brain-derived neurotrophic factor (BDNF)." (PMID 36235012, 2022). "BDNF level is decreased in AD patients, accompanied by learning and memory impairment." (PMID 35668264, 2022). "Additionally, it improved both learning and memory impairment after a week of administrating BDNF to the mice." (PMID 35628626, 2022). "BDNF inhibitor treatment improved memory impairment and LTP." (PMID 35711904, 2022). "Therefore, the activation of Wnt3/β-catenin signaling inhibits Aβ production and tau protein hyperphosphorylation and upregulates BDNF, which is necessary for synaptic plasticity and restoring learning and memory impairments." (PMID 36015156, 2022). "Moreover, LPS preconditioning in early life was found to ameliorate cecal ligation and perforation (CLP)-induced memory impairment in adult rats and to increase the expression of BDNF in the brain." (PMID 35910388, 2022). "Furthermore, BDNF and CNTF play crucial roles in the survival of neuronal cells associated with memory impairment." (PMID 35076339, 2022). "Recent studies suggest that BDNF/TrkB decrement may contribute to learning deficits and memory impairment." (PMID 34299040, 2021). "Consequently, some animal studies have used antagomiR-206 (inhibitor of miR-206) as a treatment and it further ameliorated memory impairments and BDNF dysfunction." (PMID 32944919, 2021). "The decreased BDNF signaling was related to memory impairment in aging." (PMID 34055809, 2021). "Previous studies have found that both in animal models and human studies of AD, the level of miR-206 is increased in the brain tissue and may contribute to memory impairment by blocking BDNF expression." (PMID 32944919, 2021). "Hippocampal-dependent memory impairments induced by elevated levels of brain IL-1 could occur via an IL-1 -induced downregulation in hippocampal BDNF." (PMID 33193727, 2020). "In addition, it provides evidence that adult hippocampal neurogenesis can counteract AD memory impairment, only in combination with BDNF, whereas if neurogenesis is experimentally blocked, BDNF does not exert beneficial effects." (PMID 33096634, 2020). "In summary, we found that EAEP could prevent scopolamine-induced memory impairment by regulating the cholinergic nervous system, the antioxidant defense system, and the BDNF/TrkB-signaling pathway." (PMID 32679768, 2020). "Exercise may counteract this HFD-induced BDNF reduction and memory impairment via its role in augmenting BDNF levels, via β-hydroxybutyrate alteration." (PMID 31226771, 2019). "Our data suggests that the ameliorating effects of GEGR on memory impairment could be explained, at least in part, by their protection of BDNF secretion and their receptor signaling pathway within the brain." (PMID 31623364, 2019). "In addition to isoflavone, soyasaponins are shown to prevent scopolamine-induced memory impairment in mice by preserving BDNF expression and CREB phosphorylation." (PMID 31344808, 2019). "However, we show here that F1 can be delivered by oral administration to restore memory impairment with reducing Aβ plaque and increasing pCREB and BDNF expression in AD mice, and thus is a more promising candidate to treat AD." (PMID 31488185, 2019).
memory impairment (continued). "The increase in the BDNF-pCREB level may act as a modulator of synaptic plasticity, suggesting a possible mechanism for the protective role of 5 Hz HF-rTMS on memory impairment occurring during the normal aging process." (PMID 31619982, 2019). "This study assessed whether the trimethylation of H3K9 was involved in the downregulation of BDNF expression leading to cognitive and memory impairment, and the stage at which memory processing was affected by anaesthesia and surgery." (PMID 31708739, 2019). "Moreover, the inhibition of β-secretase and γ-secretase expression and induction of BDNF expression by Lactobacillus plantarum C29 treatment alleviates memory impairment in 5XFAD-Tg mice." (PMID 31413350, 2019). "Furthermore, downregulation of pro-inflammatory myeloid cell activity via the type 2 cytokine IL-4 produced by T cells has been associated with increased release of brain-derived neurotrophic factor (BDNF) and reversal of memory impairment." (PMID 31352901, 2019). "In addition, BJIGT administration improved memory impairments and reversed decrements to the expression of the neuronal marker NeuN and neurotrophic growth factor BDNF in an AD-like mouse model." (PMID 30544702, 2018). "In our experiments, we found a memory impairment caused by BDNF-ASO only in the similar, but not in the dissimilar, condition." (PMID 29085903, 2017). "Furthermore, Rg1 was shown to repair hippocampal long-term potentiation (LTP) and improved memory impairment in APP/PS1 mice, likely through facilitating the clearance of AD-associated proteins and activating the BDNF-TrkB pathway." (PMID 29204248, 2017). "The purpose of this study is to investigate whether the BDNF‐TrkB signalling pathway is involved in propofol‐induced learning and memory impairments." (PMID 27297627, 2016). "In addition to modulating synaptic function and plasticity, BDNF improves spatial learning and protects against memory impairment and neurodegeneration, in part by preventing neuronal death." (PMID 27768775, 2016). "For example, in adult rats, exogenous administration of BDNF into the hippocampus protects from the development of stress-induced learning and memory impairment, and stress-induced impairment of learning and memory is marked by a decrease in hippocampal levels of BDNF mRNA." (PMID 27721996, 2016). "Additionally, the TrkB agonist 7,8‐DHF can ameliorate learning and memory impairments by facilitating the expression of BDNF and TrkB." (PMID 27297627, 2016). "However, at 16 weeks later, E/S and E/P group showed memory impairment, and decreased level of BDNF mRNA." (PMID 27919226, 2016). "A previous study involving mice with scopolamine-induced memory impairments found that E. ulmoides bark effectively improved the latency time in the Morris water maze test, increased BDNF expression, and inhibited AChE activity by enhancing cholinergic signaling." (PMID 26075266, 2015). "Indeed, recent reports indicate that administration of a small molecule TRKB agonist or BDNF delivery via a viral vector reversed memory impairments seen transgenic AD model mice." (PMID 24732467, 2014). "Finally, we assessed the role of the brain-derived neurotrophic factor (BDNF)-TrkB signaling pathway in mediating (S)-ketamine’s beneficial effects on spatial working memory impairment in CCI mice, considering the pathway’s established connection with (S)-ketamine’s other actions." (PMID 38332676, 2024). "All earlier and our present results indicated that iron administered to rats in the neonatal period induced an increase in oxidative stress leading to changes in the brain monoamine levels and decreased BDNF mRNA expression which may play a role in iron-induced memory impairment in adult rats." (PMID 39012420, 2024).
memory impairment (continued). "It induces learning and memory impairments in animals and humans by elevating AChE activity, increasing oxidative stress, decreasing biogenic amine levels, and suppressing the expression of genes related to memory processes, such as BDNF and CREB, in the hippocampus and cortex." (PMID 38339117, 2024). "Moreover, FRU, but not GLU, consumption evoked memory impairment in rats and was associated with decreased brain-derived neurotrophic factor in the hippocampus." (PMID 37229474, 2023). "Alterations in brain-derived neurotrophic factor (BDNF) may contribute to memory impairment." (PMID 37218868, 2023). "In addition, a previous study has reported that fluoxetine, a selective serotonin reuptake inhibitor (SSRI) antidepressant, mitigates memory impairments and depletion of hippocampal neurogenesis in rats caused by VPA associated with decreasing of BDNF levels in the hippocampus." (PMID 35873801, 2022). "In order to confirm whether the deletion or decline of neurotrophic factors is involved in memory impairment in aged rats, we detected brain-derived neurotrophic factor (BDNF) and cAMP response element-binding protein (CREB) as the crucial functional proteins for memory formation and consolidation." (PMID 32390823, 2020). "The protective effects of elamipretide on memory impairment in mice may be related to its mitochondria-targeted antioxidant properties, facilitating the modulation of BDNF signaling, and increasing the synaptic structural complexity in the mouse brain hippocampus." (PMID 31747905, 2019). "Additionally, the possible mechanisms underlying the neuroprotective effects of MTG were assessed in a rat model of PTSD, and the relationships between stress-stimulated cognition and memory impairment and BDNF and CREB expressions and inflammation in the hippocampus region were evaluated." (PMID 29973144, 2018). "Nevertheless, both IL-1β and BDNF are recognized as key players (upstream of Synapsin-1) in synaptic plasticity, and their dysregulation may also correspond to hippocampal related memory impairments." (PMID 26566284, 2015). "Ketamine primarily affects the cortex, amygdala, and hippocampus, the main neurocircuitry important to PTSD, increases brain-derived neurotrophic factor (BDNF) promoting synaptogenesis, and blocks stress-related memory impairment." (PMID 40777154, 2025). "In conclusion, studies show that the upregulation of specific genes and neuronal proteins, including Arc, BDNF (Brain-Derived Neurotrophic Factor), and NT4 (Neurotrophin-4), can limit the progression of memory impairment in diabetic mice." (PMID 38860903, 2025). "This is consistent with our experimental results, suggesting that BDNF and PSD95 signaling are closely related to the molecular mechanism of long-term memory impairment induced by early sevoflurane exposure in rats." (PMID 39664113, 2024). "We investigated the effects of treadmill exercise and intranasal insulin on learning and memory impairment and the expression of IGF1, BDNF, and GLUT4 in hypothalamus." (PMID 38987609, 2024). "Finally, we sought to assess whether fecal microbiota transplantation would restore spatial learning and memory impairment via regulating microglial M1/M2 phenotypes and the subsequent change of the BDNF signaling system in the hippocampi of chronically METH-exposed mice." (PMID 37212669, 2023). "Animal studies have also emphasized that the upregulation of BDNF and CREB proteins in the hippocampus improves memory impairment in experimental epilepsy models." (PMID 37456525, 2023).